TTR (transthyretin)
Diseases named in the same sentence as TTR in open-access papers (continued):
Sharing a sentence is not in itself a finding about the gene and the disease.
amyloidosis (continued). "To date, no other case featuring wild-type transthyretin amyloidosis (wtATTR) concurrently with a chromosomal duplication affecting both cardiac myosin heavy chain genes has been reported in the literature." (PMID 39963604, 2025). "There was no indication for prescribing disease-modifying drugs, such as transthyretin tetramer kinetic stabilizers for ATTRwt amyloidosis, because of no apparent myocardial amyloid deposits." (PMID 40557028, 2025). "The absence of systematic screening for cardiac amyloidosis, particularly wild‐type transthyretin amyloidosis in elderly patients, limits our ability to determine whether RASP reflects myocardial fibrosis, amyloid infiltration, or a combination of both." (PMID 40714907, 2025). "In addition to liver transplantation, the clinical efficacy of transthyretin (TTR) tetramer stabilisers and TTR gene silencers in hereditary ATTR (ATTRv) amyloidosis has been established." (PMID 40406049, 2025). "This analysis revealed a complete wild-type TTR gene sequence, indicating the absence of an inherited form of transthyretin amyloidosis." (PMID 39963604, 2025). "Rodent models began with transgenic mice overexpressing TTR-Val30Met, which yielded only sparse amyloid in the kidney, gut and cardiovascular organs, without peripheral neuropathy involvement." (PMID 41295360, 2025). "While the abundance of TTR was lower than IGKL (since TTR represented the minor component in this mixed amyloidosis sample), it was still notably higher than in non-ATTR cases, where TTR is typically not detected in significant amounts." (PMID 40701201, 2025). "In wild-type transthyretin amyloidosis(ATTRwt), misfolded transthyretin proteins are deposited not only in themyocardium but also in valvular tissue, including the aortic valve." (PMID 40927094, 2025). "Genetic testing of the transthyretin gene revealed no mutations, leading to a diagnosis of wild-type ATTR (ATTRwt) amyloidosis." (PMID 40546628, 2025). "All three patients had a large IgG titer against TTR amyloid, a determination which was absent in previous amyloid patients." (PMID 40943848, 2025). "However, bisphosphonate scintigraphy is the only non-invasive imaging method that can definitively confirm a diagnosis of transthyretin (ATTR) amyloidosis, after ruling out light chain (AL) amyloidosis." (PMID 40507496, 2025). "We found an increase in H/WB ratio in the ATTRv amyloidosis patients treated with TTR-stabilizers, which has never been reported before." (PMID 37843599, 2024). "The phase 3 NEURO-TTRansform trial showed eplontersen treatment for 65 weeks reduced transthyretin (TTR), halted progression of neuropathy impairment, and improved quality of life (QoL) in adult patients with hereditary TTR-mediated amyloidosis with polyneuropathy (ATTRv-PN), vs. historical placebo." (PMID 39138650, 2024). "Data from the global Transthyretin Amyloidosis Outcome Survey (THAOS) registry demonstrated that up to one-third of asymptomatic transthyretin gene carriers (36.2% Val30Met, 34.6% non-Val30Met) develop amyloid disease within a median of 2.2 years." (PMID 39768780, 2024). "Genetic testing for TTR is also important because even if a biopsy does not prove amyloid, it can make the diagnosis of ATTRv amyloidosis, allowing for early treatment." (PMID 39347301, 2024). "The most tissue-damaging species within TTR-amyloidosis is not yet fully elucidated and while amyloid deposits can disturb organ function soluble oligomers have been shown to exert a cytotoxic effect." (PMID 39615680, 2024). "Unique IgM molecules (catabodies), which were isolated from pools of blood serum obtained from healthy individuals with no history of amyloidosis, were found to hydrolyze TTR fibrils but not TTR tetramers." (PMID 39338387, 2024). "Some studies have reported non-cardiac manifestations of amyloidosis in TTR V142I carriers, including polyneuropathy and carpal tunnel syndrome, though the actual sample sizes of older patients were small." (PMID 38541013, 2024).
amyloidosis (continued). "We then sequenced the 27 patients with a diagnosis of heart failure or arrhythmia who did not carry TTR V142I, i.e., they had the TTR V142V wildtype but also had other amyloidosis-related diagnoses." (PMID 38541013, 2024). "Particularly, the involvement of TTR V30M in the heart of ATTRV30M amyloidosis has not been completely understood specifically in terms of implicated cellular pathways, heart function and cardiac physiology." (PMID 36968272, 2023). "By targeting misfolded transthyretin (TTR), CRISPR/Cas9 has been used in the treatment of transthyretin (ATTR) amyloidosis by targeting misfolded transthyretin (TTR), and the safety and pharmacodynamic effects of NTLA-2001 have been evaluated in an ongoing clinical study." (PMID 37051232, 2023). "All these findings confirm that the effects of amyloidosis on the brain and the eye are not dependent on TTR synthesized by the liver but on TTR produced respectively by the choroid plexus and the eye." (PMID 37357518, 2023). "Here, we show that surgically harvested LFs from LSS patients exhibited significantly increased thickness when transthyretin (TTR), the protein responsible for amyloidosis, was deposited in LFs, compared to those without TTR deposition." (PMID 37973808, 2023). "Vutrisiran (ALN-TTRSC02) is in Phase III clinical trials for the treatment of transthyretin (ATTR)-mediated amyloidosis with (NCT04153149) or without (NCT03759379) cardiomyopathy." (PMID 35269876, 2022). "Most but not all deposits of cardiac amyloid with mutant and wild-type transthyretin are detected by bisphosphonate scintigraphy." (PMID 35204645, 2022). "In ClinVar, the variant is classified as a variant of uncertain significance (two submissions) and once with the condition amyloidogenic transthyretin amyloidosis, but there is no literature on individuals with TTR-related conditions with this genotype." (PMID 36494773, 2022). "This manuscript reports the structure of a pathologically relevant wild type ATTR amyloid fibril from systemic non-hereditary transthyretin amyloidosis." (PMID 36302762, 2022). "Unlike inherited TTR amyloidosis, in which a change in amino acid sequence destabilizes the native transthyretin molecule, the amyloid protein in ATTRwt does not show an altered amino acid sequence." (PMID 36071866, 2022). "Conformation-specific monoclonal antibodies are very promising and would allow clearance of the amyloid deposits without affecting the physiological TTR." (PMID 35456241, 2022). "On average, patients with amyloid deposition showed a higher number of digits affected compared with negative TTR deposition." (PMID 36551982, 2022). "Wild type transthyretin-derived amyloid (ATTRwt) is the major component of non-hereditary transthyretin amyloidosis." (PMID 36302762, 2022). "The present study clearly shows that an amyloid fibril composition of only full-length TTR (fibril type B) is consistent over time in ATTRVal30Met amyloidosis patients and does not develop into fibrils with large amounts of fragmented TTR (fibril type A)." (PMID 35358243, 2022). "By cross-referencing medication orders and reconciliations, we confirmed that no additional individuals with P/LP TTR variants were prescribed ATTR therapy—specifically tafamidis, patisiran, inotersen, or diflunisal—to raise suspicion of diagnosed amyloidosis." (PMID 34746851, 2021). "In a revealing experiment, and using an AD transgenic mouse model with TTR genetic reduction (AD/TTR+/-), it was reported that IDIF administration resulted in decreased amyloid burden and total Aβ brain levels, and in the improved cognitive function of the animals." (PMID 32197355, 2020). "TTR gene silencing therapy with an antisense oligonucleotide (ASO) (inotersen) or a small interfering RNA (siRNA) (patisiran) is a recent, more promising therapeutic strategy for ATTRv amyloidosis." (PMID 33316911, 2020).
amyloidosis (continued). "There are no licensed treatments that arrest disease progression and TTR amyloidosis is thus an important unmet medical need." (PMID 30018138, 2018). "On the basis of these data, we expect that transgenic worms forming toxic TTR aggregates may be a suitable animal model of ATTR amyloidosis and can be used to screen drug candidates that would cure and/or prevent amyloidosis." (PMID 30552363, 2018). "The salutary effects of two such genes (TTR and ITMB2) were quite unexpected since by themselves both protein products were clearly amyloidogenic and responsible for distinct forms of clinically relevant human amyloidosis." (PMID 28360830, 2017). "Grouping the amyloid cases according to the type of amyloidosis revealed that the peptide mass of TTR was not exclusively detected in tissue samples with ATTR amyloid." (PMID 28994248, 2017). "Together with these previous findings, our data suggest that TTR non-coding variation and its effect on transcription regulation are strong candidates as casual factors in the non-inherited form of TTR amyloidosis." (PMID 28335735, 2017). "Gamma scintigraphic imaging with 99mTc-labeled 3,3-diphosphono-1,2 propanodicarboxylic acid (99mTc-DPD) can provide accurate imaging of ATTR cardiac amyloid, but not cardiac AL or TTR amyloid deposits in organs other than the heart." (PMID 26664895, 2015). "The differential interaction and processing of an aggregation-prone, disease-associated transthyretin variant with human cardiac cells, compared with a non-disease associated transthyretin mutant may explain the basis of the early events of tissue damage in the transthyretin amyloidoses." (PMID 25395306, 2015). "There was no effective treatment for TTR amyloidosis until orthotopic liver transplantation was introduced in 1991." (PMID 26400472, 2015). "When there is no known family history of amyloidosis, the diagnosis of TTR-FAP should be considered in patients with a progressive, length-dependent axonal polyneuropathy predominantly affecting temperature and pain sensation." (PMID 23425518, 2013). "Immunoglobulin light chain–related CMP (AL‐CMP) features rapidly progressive HF with an extremely poor prognosis compared with a CMP due to the deposition of mutant (ATTR) amyloidosis or wild‐type (senile systemic amyloidosis, SSA) transthyretin (TTR) proteins." (PMID 23537813, 2013). "Most of the TTR-related amyloidosis does not affect the central nervous system (CNS) but there are few TTR mutations (about 10 variants) associated with TTR amyloid deposition in the leptomeninges." (PMID 22253829, 2012). "Transthyretin (TTR) is one of thirty non-homologous proteins whose misfolding, dissociation, aggregation, and deposition is linked to human amyloid diseases." (PMID 19621084, 2009). "While wild-type TTR amyloidosis also exists, it is a distinct, non-hereditary form of the disease." (PMID 40406766, 2025). "Additionally, tafamidis does not effectively inhibit seeded TTR aggregation, where extracted amyloidogenic fibrils from patients with TTR amyloidosis are used as seeds for aggregation assays in vitro." (PMID 40816471, 2025). "However, it should be noted that amyloidosis codes are not specific to hATTR and include wild type TTR and primary amyloidosis, for example." (PMID 41282679, 2025). "Therefore, a negative fat pad biopsy does not eliminate transthyretin amyloidosis as the culprit of disease." (PMID 41149834, 2025). "In this study, we demonstrate that patients with transthyretin cardiac amyloidosis (ATTR-CA) exhibit significantly reduced native T1 values in several anatomical structures of the wrist, which are typically involved in amyloidosis, compared with healthy controls." (PMID 41156243, 2025).
amyloidosis (continued). "More than 150 variants of TTR have been described worldwide and most of them are involved in three TTR-related amyloid diseases (ATTR), namely, familial amyloid cardiomyopathy, familial amyloid polyneuropathy, and a rare form of amyloidosis called oculoleptomeningeal amyloidosis." (PMID 38925327, 2024). "By contrast, for peripheral amyloidoses, where BBB traversal is not required, such as those caused by transthyretin or serum amyloid A1, a more direct route to testing of therapeutic efficacy of the designs could be available." (PMID 38503834, 2024). "PYP scan was performed in 6/10 patients and was negative for TTR amyloidosis in all cases." (PMID 39417970, 2024). "This concurs with discussions triggered by now established non-biopsy diagnosis of cardiac wild-type transthyretin (ATTRwt) amyloidosis and treatment options that have been approved or are in the advanced stage of clinical investigation (e.g. NCT04136171, NCT03997383)." (PMID 38341596, 2024). "The pathogenesis of tissue tropism and damage in transthyretin amyloidosis (ATTR) is still not well understood, but it has been proposed that local features of endoplasmatic reticulum-assisted folding and degradation of TTR may determine tissue selectivity of amyloid accumulation." (PMID 38410247, 2024). "In addition to several rare and chronic inflammatory diseases (AA), monoclonal immunoglobulin light-chain (AL), hereditary transthyretin (m-ATTR), and non-mutant or wide-type transthyretin (wt-ATTR) amyloidosis are present in 98% of the cases." (PMID 39124597, 2024). "Similarly, after genotyping 666 AA patients with heart failure or arrhythmia, TTR V142I carriers appeared to be clinically indistinguishable based on amyloid-related non-cardiac diagnoses from those who did not carry the allele." (PMID 38541013, 2024). "Finally, we compared the demographic and clinical characteristics of participants with hATTR (TTR-positive) and participants with ATTRwt (TTR-negative and also meeting the inclusion criteria for ‘suspicion of amyloidosis, based on imaging or biopsy’)." (PMID 39458146, 2024). "One piece of evidence potentially supporting this assertion is from a mouse model of TTR amyloidosis in which age-dependent deposition of TTR aggregates in the heart correlate with altered expression of some UPR target genes in the liver, the primary site of TTR synthesis." (PMID 35191945, 2022). "Hence, the presence of ATTR amyloid fibrils consisting of a mixture of full-length TTR and large amounts of TTR fragments in mainly elderly ATTR Val30Met amyloidosis patients cannot be explained by differences in disease duration and the “age” of the amyloid deposits." (PMID 35358243, 2022). "The current standard of care (SoC) focuses on preventing further amyloid formation and deposition, either with anti-plasma cell dyscrasia (anti-PCD) therapies in light-chain (AL) amyloidosis or stabilizers of transthyretin (TTR) in transthyretin amyloidosis (ATTR)." (PMID 36606280, 2022). "Taken together, central TTR knockdown might be helpful or even needed to stop CNS ATTRv amyloidosis, which is, without doubt, a dreadful and life-limiting condition." (PMID 34719408, 2021). "Based on their TH-like activities and efficacy as TTR stabilizers in Aβ-related pathologies, we propose that GC-1, together with its analogs, IS25 and TG68, could be novel candidates as multi-functional drugs for TTR amyloidosis, and related pathologies." (PMID 33800546, 2021). "Thus, there is no reason to consider wild type TTR amyloidosis and familial TTR amyloidosis as separate diseases." (PMID 33203794, 2020). "Moreover, this patient was negative on the TTR gene test, excluding the likelihood of TTR amyloidosis." (PMID 33019488, 2020).
amyloidosis (continued). "Acquired monoclonal immunoglobulin light-chain amyloidosis (AL), the hereditary, transthyretin (TTR)-related form (ATTRm), and wild-type (non-mutant) TTR-related amyloidosis (ATTRwt) systemic “senile” amyloidosis account for more than 90% of all cardiac amyloidosis (CA)." (PMID 31134330, 2020). "The formation of non-native monomers is the key step in TTR amyloidosis." (PMID 31117178, 2019). "It is the second description of ATTR in a Bangladeshi patient, with the first case being reported in a family with polyneuropathy associated with the Ile73Val TTR variant, without vitreous amyloidosis." (PMID 28802308, 2017). "Familial amyloidoses are rare diseases, especially in nonendemic areas, and are divided into three subtypes that present with different involvement of the peripheral nervous system: transthyretin (TTR), apolipoprotein A-I and gelsolin." (PMID 25471118, 2014). "Interestingly, aggregation pathways involving dissociation of oligomers are well-established for several proteins undergoing pathological β-aggregation, such as transthyretin and SOD1, respectively involved in familial amyloidotic polyneuropathy (FAP) and ALS, two amyloid-forming diseases." (PMID 24098542, 2013). "On further review, it was felt that the presentation was not particularly consistent with AL Amyloidosis given her demographics and the absence of other organ involvement or an elevated Ig fraction, and so the biopsy was sent for further analysis of transthyretin deposition." (PMID 20062619, 2009). "Furthermore, this study revealed higher LS values in patients with AL-A liver involvement compared to AL-A without liver involvement and transthyretin amyloidosis patients with cardiac involvement as a control group, since liver involvement is not a feature of transthyretin amyloidosis." (PMID 40593362, 2025). "To investigate whether TTR, a major causative factor of ATTR amyloidosis (which is the same type of amyloidosis as Alzheimer’s disease), interacts with the EV membrane surface, we analyzed the interaction using purified TTR and EVs derived from HEK293T and NIH3T3 cells that do not produce TTR." (PMID 35402512, 2022). "Indeed, the interaction of GC-1 with TTR and its suppressive activity against TTR amyloidosis was reported once, yet it was not followed by further studies to elucidate its detailed molecular mechanism and to expand chemical diversity and functionality of GC-1." (PMID 33800546, 2021). "Novel disease-modifying treatments such as transthyretin stabilizers (diflunisal, tafamidis) and RNA interference agents (patisiran, inotersen) may have an impact on the natural history of nOH in patients with hereditary TTR amyloidosis, although dedicated studies are yet to be performed." (PMID 31452021, 2019). "Since the wild-type transthyretin amyloidosis could not entirely explain her clinical presentation and evaluation, further studies were conducted in a sequential manner, thus leading to a diagnosis of Pompe disease explaining her presenting signs and symptoms including her macroglossia." (PMID 30510819, 2018). "Therefore, although we generated the C. elegans model system in body wall muscle cells for the TTR study, we still need to establish a secretion system of TTRWT, TTRV30M, and TTR81–127 and a corresponding detection system in C. elegans to fully understand the mechanism of TTR amyloidosis." (PMID 30552363, 2018). "In addition to familial TTR- associated forms of amyloid, senile systemic amyloidosis (SSA) is a nonhereditary, late onset sporadic form of TTR amyloidosis that is typically related with wild-type TTR amyloid deposition in the heart, leading to cardiac dysfunction and ultimately death." (PMID 27197872, 2016). "An endomyocardial biopsy showed nodular and interstitial deposits of amyloidosis (CRSR +) and was positive for TTR but negative for lambda or kappa chains." (PMID 39407234, 2024).